PCNA (proliferating cell nuclear antigen)
Diseases named in the same sentence as PCNA in open-access papers (continued):
Sharing a sentence is not in itself a finding about the gene and the disease.
Obesity (6 papers, 2014 to 2024). Accumulation of substantial excess body fat. "Hypothesizing that changes in the placenta upon n-3 LCPUFA intervention during pregnancy are involved in the programming of offspring obesity risk, we discovered that placental CDK6 and PCNA mRNA levels were positively correlated with offspring birth weight and birth weight percentiles." (PMID 25348288, 2014). "A comparison of vimentin protein levels in lysates from tumor tissues between HFD and HFD-IF groups revealed that IF diminished obesity-induced vimentin expression, but PCNA protein levels were no different in these two groups." (PMID 38999849, 2024). "TNF-α downregulated some of the DNA damage repair genes, which are also altered by obesity: PARP1 (−49.3%, P = 0.008), BLM (−46.9%, P = 0.02), FEN1 (−25.5%, P = 0.04), and PCNA (−38.0%, P = 0.008), but did not affect HDAC1 and Ku70 gene expression." (PMID 39092995, 2024).
anemia (5 papers, 2012 to 2025). A reduction in the number of red blood cells, the amount of hemoglobin, and/or the volume of packed red blood cells. "In human cells Usp1 deubiquitylates PCNA as well as the Fanconi's anaemia protein FANCD2." (PMID 22829782, 2012).
astrocytomas (5 papers, 1997 to 2020). "Previous studies of PCNA protein expression levels in astrocytoma and oligoastrocytoma indicated that increased expression was correlated with increasing tumour grade and decreasing patient survival rates." (PMID 28562655, 2017). "However, neural cell adhesion molecule (NCAM) levels were down-regulated as the malignancy of astrocytomas increased, and this effect is inversely correlated with PCNA." (PMID 29089868, 2017). "Moreover, the existence of (a) molecular mechanism(s) inhibiting the Dnmt1/PCNA/UHRF1 interaction is also supported by the paradoxical situation seen in astrocytoma cells." (PMID 20613874, 2010). "Indeed, the astrocytoma cells harbor a low level of Dnmt1/PCNA/UHRF1 interaction, whereas these cells, highly proliferative, are supposed to harbor a high level of the Dnmt1/PCNA/UHRF1 interaction according to the idea that the maintenance DNA methylation is a DNA replication-dependent process." (PMID 20613874, 2010).
cervical intraepithelial neoplasia (5 papers, 2013 to 2023). "Real time PCR, ROC curve and Logistic regression analysis showed that human papillomavirus infection, TCT severity, ABCG2, TDG, PCNA were independent risk factors for cervical intraepithelial neoplasia." (PMID 35379200, 2022). "PCNA expression was associated with high-risk HPV and the progression of cervical intraepithelial neoplasia (CIN)." (PMID 36834892, 2023). "Finally, we did not observe any evident differences between PHK18A1 and PHK18B1 in forming epithelia in organotypic culture: both showed hyperplasia, in addition to high levels of CK10, PCNA, and p16 throughout the tissue, compatible with cervical intraepithelial neoplasia." (PMID 34200583, 2021). "At the same time, the early warning model including ABCG2 + PCNA+TDG genes provided a new idea and target for clinical prediction and blocking the evolution of cervical intraepithelial neoplasia malignant transformation from the aspect of cervical microbiological related genes." (PMID 35379200, 2022).
COVID-19 (5 papers, 2020 to 2024). A disease caused by infection with severe acute respiratory syndrome coronavirus 2. "We, therefore, propose that the transport of PCNA to the cytoplasm and its association with M could be a virus strategy to manipulate cell functions and may be considered a target for COVID-19 therapy." (PMID 35677658, 2022). "Meanwhile, the transcripts for genes involved in cell proliferation, such as Ki67 and PCNA, were significantly downregulated in the COVID-19 group as compared to the control group (p < 0.0001)." (PMID 39866583, 2024). "Our results indicate high expression of both markers in COVID-19 patient, suggesting the involvement of both PCNA and γH2AX in SARS-CoV-2 infection in vivo." (PMID 35677658, 2022). "Our results indicate a potential use of PCNA and nuclear translocation inhibitors as treatments for COVID-19." (PMID 35677658, 2022). "We also observed an increase in PCNA and γH2AX expression in the lung of a COVID-19 patient by immunohistochemistry." (PMID 35677658, 2022). "We then compared PCNA and γH2AX expression levels in lung sections obtained from control and COVID-19 patients through immunohistochemistry assay." (PMID 35677658, 2022). "Furthermore, in an activated state, for example infection with COVID-19, PCNA was found to be elevated in the cytosol of patients with active infection." (PMID 39205238, 2024). "We also found a high expression of PCNA and γH2AX in a COVID-19 patient." (PMID 35677658, 2022). "Our single-cell analysis showed that, in patients with severe/critical COVID-19, CD8+ T cell clusters were found to have a proliferative phenotype with highly expressed MKI67 and PCNA." (PMID 37628961, 2023).
dysplasia (5 papers, 2015 to 2025). A usually neoplastic transformation of the cell, associated with altered architectural tissue patterns. "In oral potentially malignant disorders (OPMD), PCNA miR-375 levels are lower in patients with dysplasia, which indicates its potential as a sensitive marker." (PMID 41388527, 2025).
Infertility (5 papers, 2010 to 2021). "In mice the only characterised PCNA variant is the site directed mutation of lysine-164 to arginine, which results in infertility and in alterations to the somatic hypermutation spectrum due to the requirement for ubiquitination on PCNA Lys164 for the recruitment of Polη." (PMID 28073635, 2017). "Shiraishi co-workers believed that proliferating cell nuclear antigen expression which has an important role in DNA synthesis, decreases in infertile men with varicocele." (PMID 29766149, 2018). "Niacin, CoQ10, FEN, triptorelin, and carvacrol can be considered effective protective therapies for the cytotoxic treatment of infertile women with POF, and PCNA may serve as a diagnostic and prognostic marker." (PMID 34721621, 2021). "Furthermore, our data demonstrated that the out-of-phase endometrium from infertile and abortion patients expresses decreased PCNA levels, showing that cell proliferation is diminished in this endometrial tissue." (PMID 20969784, 2010). "Thus, PCNA may serve as an emerging target for the treatment of EM-related infertility in women of childbearing age." (PMID 34721621, 2021). "Expressions of Proliferating Cell Nuclear Antigen (PCNA) as a marker of cell proliferation, and of cleaved caspase-3 as a marker of apoptosis, were assessed by immunohistochemistry in the luteal in-phase and out-of-phase endometrium from infertile and recurrent abortion patients." (PMID 20969784, 2010).
lymph node metastasis (5 papers, 2004 to 2023). "In the NSCLC group, the positive rates of semaphorin-3A and MMP-14 expression were relevant to pleural invasion, lymph node metastasis, the number of metastatic lymph nodes, the degree of differentiation, vascular invasion and PCNA expression." (PMID 24765144, 2014). "It has been shown taht PCNA was significantly related to lymph node metastasis in gastric cancer." (PMID 37185598, 2023). "The expression of PCNA correlated with rectal cancer invasion and lymph node metastasis." (PMID 35268705, 2022). "Their expression levels were analyzed against clinical characteristics, including pleural invasion, lymph node metastasis, the number of metastatic lymph node, degree of differentiation, vascular invasion and proliferating cell nuclear antigen (PCNA) expression." (PMID 24765144, 2014).
nasopharyngeal carcinoma (5 papers, 2016 to 2024). A carcinoma arising from the nasopharyngeal epithelium. "It has been shown that NQO1 expression is enhanced, while MMP9 and PCNA expression is downregulated with the declining deuterium concentration in nasopharyngeal carcinoma cells (NPCs)." (PMID 38732643, 2024). "Proliferating cell nuclear antigen (PCNA) is closely related to cellular DNA synthesis and can be used to label cells that are mitotically active; interestingly, it is highly expressed in nasopharyngeal carcinoma cells." (PMID 32215033, 2020). "In vivo assays showed that FA-CD-PLLD/DOC/MMP-9 could inhibit HNE-1 tumor growth and decrease PCNA expression effectively, indicating a promising strategy for nasopharyngeal carcinoma therapy." (PMID 27259274, 2016).
Parkinson disease (5 papers, 2014 to 2020). A progressive degenerative disorder of the central nervous system characterized by loss of dopamine producing neurons in the substantia nigra and the presence of Lewy bodies in the substantia nigra and locus coeruleus. "Evidence of cytoplasmic PCNA also comes from a study showing the impact of the S-nitrosylation status of PCNA on the apoptotic pathway in a Parkinson disease cell model, and a more recent paper reporting that interaction of cytoplasmic PCNA with angiogenin." (PMID 32597793, 2020). "Moreover, mitogenic markers such as Proliferating Cell Nuclear Antigen, pRb, cyclins, and CDKs have been found in CNS samples of Alzheimer’s and Parkinson’s disease patients while Huntington’s disease and ALS patients demonstrated elevated CNS levels of pRB and cyclin D1." (PMID 31369591, 2019).
pulmonary hypertension (5 papers, 2018 to 2024). Increased pressure within the pulmonary circulation due to lung or heart disorder. "Medial hypertrophy of pulmonary resistance vessels occurred in parallel to an increased number of PCNA-positive proliferating vascular cells in MCT-induced pulmonary hypertension." (PMID 35521617, 2018). "(2015) during a study on MCT induced pulmonary hypertensive rats shows that the treatment with W. somnifera can reduce RVP and RVH, also could reduce the expression of PCNA." (PMID 32226378, 2020).
rectal cancer (5 papers, 2009 to 2024). A primary or metastatic malignant neoplasm that affects the rectum. "Administration of various SSAs resulted in a reduction in tissue expression of proliferative antigens, i.e., Ki-67 in 4/12 patients with rectal cancer (RC) and proliferating cell nuclear antigen (PCNA) in 6/10 patients with CRC versus control." (PMID 38540191, 2024). "The first factor, high proliferative activity with Ki67 as the marker, was earlier found to correlate with PCNA immunostaining, and mitotic counts after radiation of rectal cancer." (PMID 19491899, 2009).
Renal cyst (5 papers, 2016 to 2024). A fluid filled sac in the kidney. "Given that PRAS40 depletion decreased PCNA expression in Tsc2-depleted renal cysts, we checked the significance of PRAS40 in the proliferation of Tsc2−/− MEFs." (PMID 39333852, 2024). "Immunofluorescence assays revealed that the PCNA expression in the nuclei of renal cyst cells and dilated tubule cells of NPHP1 mice was slightly increased compared with that in other tubular cells in NPHP1 mice and normal tubular cells in WT mice." (PMID 37583898, 2023). "PCNA, β‐catenin, and Smad2 were elevated in cystic kidneys compared to age‐matched controls by 18 days of age, and the phosphorylated forms of both Erk and ribosomal protein S6 were elevated compared to wild‐type controls by 26 days of age." (PMID 27356569, 2016). "Although a decrease in PCNA, ribosomal protein S6, and β‐catenin levels occurred in cystic kidneys after 26 days, levels of these markers remained elevated compared to age‐matched control kidneys through 180 days of age." (PMID 27356569, 2016). "Akt1s1 deletion reduced the number of PCNA-positive cells in renal cyst epithelial cells." (PMID 39333852, 2024). "To assess the mechanisms for 17a-dependent delay in posttreatment regrowth of renal cysts/cystadenomas, we performed immunohistochemical staining of p-S6 (Ser235/236) and proliferating cell nuclear antigen (PCNA), as well as TUNEL assay, in kidneys from mice withdrawn from treatments." (PMID 36927688, 2023). "GA-A downregulates the Ras/MAPK signaling pathway in a dose-dependent manner, inhibits the expression of proliferating cell nuclear antigen (PCNA), alleviates the growth and progression of renal cysts, and delays the progression of autosomal dominant polycystic kidney disease (ADPKD)." (PMID 39459639, 2024).
renal fibrosis (5 papers, 2021 to 2024). A final common manifestation of a wide variety of chronic kidney diseases characterized by glomerulosclerosis and tubulointerstitial fibrosis. "Consistent with the PCNA expression, the degree of renal fibrosis was more severe in UA-group mice, and fibrosis could be reversed by eplerenone." (PMID 34386059, 2021). "Also, the levels of damage markers in renal fibrosis, including ED-1 α-SMA, IL-6, IL-1β, TNF-α, TGF-β, NF-κB mRNA, CCL-2, CCL-5, collagen I, FN, collagen IV, and PCNA are decreased." (PMID 36268508, 2022).
cholangiocarcinoma (4 papers, 2018 to 2024). A carcinoma that arises from the intrahepatic biliary tree (intrahepatic cholangiocarcinoma) or from the junction, or adjacent to the junction, of the right and left hepatic ducts (hilar cholangiocarcinoma). "To delve into the underlying mechanism of EIF3B’s influence on cholangiocarcinoma, we further investigated its impact on PCNA." (PMID 38687509, 2024). "Immunohistochemical (IHC) analysis was employed to detect EIF3B/PCNA expression in cholangiocarcinoma." (PMID 38687509, 2024). "This shed light on a novel regulatory mechanism involving EIF3B, SYVN1, and PCNA in cholangiocarcinoma pathogenesis." (PMID 38687509, 2024). "The validation of the interaction between PCNA and EIF3B indicated that PCNA serves as a downstream factor regulated by EIF3B in the context of cholangiocarcinoma." (PMID 38687509, 2024). "In conclusion, our study elucidated that EIF3B played a pivotal role in promoting cholangiocarcinoma through the regulation of the PCNA and P21 pathways." (PMID 38687509, 2024). "Overall, our findings demonstrated that EIF3B was involved in cholangiocarcinoma development through targeting PCNA." (PMID 38687509, 2024). "The tumor-promoting impact of EIF3B was found to be mediated through PCNA, and the inhibition of PCNA not only suppressed the development of cholangiocarcinoma but also reversed the promotional effects induced by EIF3B overexpression." (PMID 38687509, 2024). "To confirm the contribution of PCNA to EIF3B-mediated cholangiocarcinoma progression, we established RBE cell models involving singular overexpression of EIF3B, singular silence of PCNA, and concurrent EIF3B overexpression with PCNA silencing." (PMID 38687509, 2024). "Similar to EIF3B, PCNA levels were also abundant in cholangiocarcinoma, and knocking down PCNA impeded cholangiocarcinoma development." (PMID 38687509, 2024). "In the context of cholangiocarcinoma, elevated PCNA expression designates it as a tumor promoter." (PMID 38687509, 2024). "Here, we also found that PCNA was abundantly expressed in cholangiocarcinoma tissues and cells." (PMID 38687509, 2024). "We highlight biological effects of autophagy impairment in cholangiocarcinoma showing that autophagy induction, via rapamycin, as well as caspase inhibition, via Q-VD-OPh, are able to reduce proliferation marker PCNA level, colony size and protein content of cultured cholangiocarcinoma cells." (PMID 37841311, 2023). "Also, expression of PCNA is a universal feature in cholangiocarcinoma." (PMID 38687509, 2024). "To further validate whether PCNA could reverse the inhibitory effects of EIF3B knockdown on cholangiocarcinoma, we conducted separate transfections of a PCNA overexpression plasmid and an EIF3B knockdown plasmid, as well as simultaneous transfections, in REB cells." (PMID 38687509, 2024). "Mechanistically, we identified Proliferating Cell Nuclear Antigen (PCNA) as a downstream gene of EIF3B, driving cholangiocarcinoma." (PMID 38687509, 2024). "Treatment of cholangiocarcinoma CCA cells with MAG decreased malignancy and proliferation of the cells by downregulation of PCNA, Ki67, MMP-2, -7 and -9 protein expression and inhibition of the NF-κB signaling pathway." (PMID 30103472, 2018). "In cholangiocarcinoma (CCA) cells, magnolol significantly inhibits cell growth, migration, and invasion, accompanied by decreased expression of Ki67, proliferating cell nuclear antigen (PCNA), matrix metalloproteinases 2 (MMP-2), MMP-7, and MMP-9." (PMID 31240205, 2019). "Additionally, a differential expression analysis of these genes based on cholangiocarcinoma and normal tissues samples from the TCGA database revealed significant upregulation of CDCA5, FAM111B, MCM8 and PCNA in cholangiocarcinoma, supporting their relevance in this context." (PMID 38687509, 2024).
emphysema (4 papers, 2005 to 2026). "CS-exposed mice injected with LGF, showed an amelioration of emphysema and improved lung function, which correlated with lower MMP activity and 3NT expression and higher levels of VEGF, PCNA and Nrf2." (PMID 25401951, 2014). "Together with NE and PCNA analysis, the long-term PPE/LPS exposure histopathological data showed that PM014 administration inhibited the progression of emphysema and goblet cell metaplasia." (PMID 22778777, 2012).
gastric adenocarcinoma (4 papers, 2017 to 2025). "Conversely, high expression of PCNA was associatedwith favorable outcome in stomach adenocarcinoma (STAD) (HR = 0.52, p = 0.0013)." (PMID 40657100, 2025). "The suppressive effect on cell proliferation by UA or PTX is possibly induced by the prevention of COX-2 inducing PCNA expression in gastric adenocarcinoma cells." (PMID 29190954, 2017).
HCMV infection (4 papers, 2012 to 2026). "We previously observed that HCMV infection in fibroblasts induces monoubiquitination of PCNA and, in line with observations from others, re-localization of PCNA to viral RCs (14, 28, –, 30)." (PMID 40130902, 2025). "While the mechanisms by which PCNA restricts HCMV infection remain to be defined, we report that K164 modification is important to this restriction in TB40/E infection." (PMID 40130902, 2025). "Given the role of TLS polymerases in HCMV infection and their dependence on mUb-PCNA in host cells, we sought to build on our findings by further characterizing mUb-PCNA in the context of HCMV infection." (PMID 40130902, 2025). "Altogether, this work uncovers specific contributions of PCNA to HCMV infection and highlights the complexity of this virus-host interaction." (PMID 40130902, 2025). "We show that HCMV infection induces monoubiquitination of PCNA, a modification important for recruiting TLS polymerases." (PMID 40130902, 2025). "Through studying the role of PCNA in HCMV infection, we uncovered multiple, distinct functions of PCNA and, by extension, TLS polymerases on viral genomes that deviate from their canonical function in TLS in host cell biology." (PMID 40130902, 2025). "We previously reported that vDNA synthesis induced mUb–PCNA during CMV infection." (PMID 41533576, 2026). "However, we have shown that TLS polymerases also have PCNA-independent roles in the context of CMV infection." (PMID 41533576, 2026). "Overexpression of RGS5 decreased the expression level of PCNA protein, suggesting that proliferation of ECs could be induced by HCMV infection via hypermethylation and downregulation of RGS5." (PMID 32041970, 2020). "Thus, it could be concluded that DNMT inhibitors could reverse the high expression of PCNA induced by HCMV infection." (PMID 32041970, 2020). "Here, we show that USP1, PCNA, and FANCD2, were relocalized to sites of vDNA synthesis during productive CMV infection in primary fibroblasts." (PMID 41533576, 2026). "Taken together, these data are consistent with the hypothesis that UL138 influences the deubiquitylation of mUb–PCNA and mUb–FANCD2 in CMV infection." (PMID 41533576, 2026). "Furthermore, unlike mock-infected cells, HCMV infection maintained mUb-PCNA despite increasing cell confluence." (PMID 40130902, 2025).